ALB (albumin)
Diseases named in the same sentence as ALB in open-access papers (continued):
Sharing a sentence is not in itself a finding about the gene and the disease.
tumor (continued). "One well-known potent ABM with competitive displacement ability from albumin is 4-(p-iodophenyl)butyric acid (IPBA), and various PSMA ligands with IPBA have been shown to exhibit higher accumulation and longer retention in tumor tissues than those in PSMA ligands without IPBA." (PMID 40649319, 2025). "Among the various NPs under investigation, protein-based NPs such as human serum albumin (HSA) NPs and lactalbumin NPs are emerging as promising bio-inspired nanocarriers due to their natural biocompatibility, non-immunogenicity, high drug loading ability, and tumor-targeting ability." (PMID 38276483, 2023). "The combination of albumin and ICG in a nanoparticle for NIR fluorescence imaging guided PTT with external laser irradiation has been also reported, however, the attempt to optimize the PLQY of ICG to improve the tumor diagnosis precision has not been explored." (PMID 32183838, 2020). "Interestingly, the tumor cells were found to express Bmi1, AFP and albumin, but not CK19." (PMID 26926789, 2016). "Elevations in albumin, osteopontin, and others, although not GBM specific, might suggest that peptide levels in the CSF reflect changes in the nervous system environment that could be used to determine the status of a GBM tumor." (PMID 25312641, 2014). "Although a lower extracellular ALB level is a well-known negative prognostic index of HCC, this study can suggest alternatively that a high [ALB]serum (compared with those near lesions) might exaggerate liver malignancy via TM4SF5-dependent ALB uptake and bioenergetics, leading to tumor expansion." (PMID 40186033, 2025). "Retrospectively, the fatality could be the result of the sudden withdrawal of the ascitic fluid without any cover of albumin, or the rapid reduction of atrial pressure, or the vasodilation in splanchnic bed with reduced venous return to the heart as IVC was completely occluded by tumor thrombus." (PMID 32953422, 2020).
cancer (2,319 papers, 1971 to 2026). A tumor composed of atypical neoplastic, often pleomorphic cells that invade other tissues. "This is of relevance as previous research has suggested sex-differences in the association between albumin and cancer symptoms." (PMID 41504962, 2026). "This study aimed to evaluate the association between preoperative serum albumin levels and postoperative complications, length of hospital stay, and mortality in geriatric patients undergoing cancer surgery." (PMID 41840567, 2026). "Both high calcium and low albumin were predictive of cancer risk in each of the three main ethnic groups." (PMID 40941010, 2025). "This study aims to evaluate the correlation between the serum albumin–creatinine ratio and the risk of anthracycline-induced cardiotoxicity in cancer patients." (PMID 40095884, 2025). "Subgroup analysis of the association between serum lactate dehydrogenase-to-albumin ratio and recurrence-free survival in cancer patients." (PMID 40693202, 2025). "It is known that the serum albumin concentration can change under oxidative stress, such as that associated with cancer." (PMID 40003620, 2025). "Serum albumin is a recognized biomarker of nutritional status and has been linked to comorbidities and cancer prognosis." (PMID 40936893, 2025). "The results of many studies have shown that lower levels of serum albumin are associated with poor prognosis in a variety of cancers, Including ICC." (PMID 40115790, 2025). "Previous studies have shown that lower albumin levels are associated with increased inflammation, poor prognosis, and higher mortality risk in cancer patients." (PMID 40806017, 2025). "Here, we combined live-cell imaging with LC-MS to show that metals and albumin-associated lipids in serum are crucial factors for sustaining cancer cell proliferation in culture." (PMID 40027810, 2025). "Albumin levels were inversely associated with mortality and length of stay, while arrival from a healthcare facility and cancer chemotherapy predicted having a multidrug-resistant isolate." (PMID 39601576, 2025). "On the other hand, given the complex interaction between systemic inflammation, poor nutritional status, and muscle loss in cancer progression, it is important to integrate albumin and myosteatosis into a single prognostic indicator." (PMID 41002580, 2025). "Subgroup analysis of the association between serum lactate dehydrogenase-to-albumin ratio and overall survival in cancer patients." (PMID 40693202, 2025). "Low serum albumin has been consistently associated with unfavorable prognoses and reduced survival rates in cancer patients." (PMID 40936893, 2025). "A meta-analysis showed that elevated levels of serum albumin were associated with reduced risk of vascular outcomes, all-cause mortality, some cancers, and fractures." (PMID 40168268, 2025). "Serum creatine kinase levels reflect both muscle loss and the extent of muscle damage, while serum albumin levels are known to decrease in patients with cancer cachexia." (PMID 40469669, 2025). "The systemic inflammatory status caused by cancer can decrease the concentration of albumin by increasing transcapillary escape." (PMID 40025678, 2025). "Secondary relative malnutrition and chronic gastrointestinal bleeding caused by malignant tumors contribute to chronic anemia, preventing hemoglobin and albumin levels from reaching normal values." (PMID 40565788, 2025). "Across both sexes, the strongest associations between individual blood tests and cancer were for raised platelets and low albumin, with these abnormalities being 3 to 4-fold more likely in abdominal pain patients with cancer than controls (OR 3.28–3.59)." (PMID 39799273, 2025). "Bacteraemia and increased albumin were associated with improved survival, while increasing age and reducing national survival of the underlying cancer were all associated with worse survival." (PMID 39871712, 2025).
cancer (continued). "Serum albumin, an important indicator of nutritional status and liver function, is closely linked to cancer prognosis." (PMID 40716028, 2025). "Low serum albumin levels are associated with poor nutritional status, increased tumor burden, and a worse prognosis in cancer patients." (PMID 40565133, 2025). "Another study also revealed that serum albumin was an independent VTE risk factor in patients with cancer, supporting the present study." (PMID 40168285, 2025). "Total bilirubin, albumin, and uric acid are representative endogenous antioxidants, and their protective associations have been reported in various oxidative stress-related cancers." (PMID 40427466, 2025). "It has been shown that of the three components of the CONUT nutritional status assessment—serum albumin, serum cholesterol and absolute lymphocyte count in the blood—only the lymphocyte count is associated with the prognosis in cancer patients." (PMID 40427092, 2025). "Using this defined system, we investigated cancer cell lipid consumption dynamics, finding that albumin-associated lipids are primarily consumed through a mass-action mechanism with minimal competition within or amongst lipid classes." (PMID 40930249, 2025). "High CRP and low albumin levels are markers of inflammation and disease burden, especially in cancer, and are associated with poor prognosis." (PMID 40124502, 2025). "Low serum albumin levels often result from chronic inflammation, which is a hallmark of many cancers." (PMID 41255598, 2025). "This mortality risk was confirmed by including sex, age, type of cancer, smoking habits, BMI, albumin, creatinine levels, traditional coagulation parameters (PT, aPTT, and fibrinogen), and total TFPI in regression models." (PMID 38282902, 2024). "Mangiferin-treatment (D and E) in AOM-induced foci was associated with significantly higher total proteins and albumin concentrations than in the plasma of cancer control rats." (PMID 38191592, 2024). "An elevated CAR reflects both heightened inflammation (as indicated by high CRP) and compromised nutritional status (as reflected by low albumin), both of which are associated with adverse outcomes in cancer patients." (PMID 39371828, 2024). "Alterations in serum albumin concentration are known to occur under conditions of oxidative stress, such as that associated with cancer." (PMID 39765841, 2024). "Pancreaticobiliary obstruction, PEI and lower albumin in patients with pancreatic head tumours suggests compounding effects of nutrient malabsorption and systemic inflammation on cancer‐associated cachexia, possibly contributing to shorter survival." (PMID 38123146, 2024). "Key insights from the current investigation include: i) Reduced serum albumin levels are linked to an increased risk of cancer mortality." (PMID 38500655, 2024). "showing that men with serum albumin<40 g/L were at higher risk of cancer mortality, two following studies including 17548 and 93913 men did not confirm such association." (PMID 39010980, 2024). "Albumin reflects nutritional status and response to inflammation and is associated with treatment outcomes in cancer patients." (PMID 38803531, 2024). "This study demonstrates that albumin is a significant predictor of cancer mortality in both aggressive and less aggressive cancers, supporting its potential as a stable risk predictor for the most common cancers." (PMID 38500655, 2024). "In our cohort of 448 cancer patients, low albumin and low BMI were associated with higher 90-day mortality." (PMID 39414641, 2024). "The Prognostic Nutritional Index (PNI) integrates lymphocyte and serum albumin data to reflect the nutritional and immune status of patients with cancer, and is associated with the prognosis of patients with breast, colorectal, and non-small cell lung cancers." (PMID 39624689, 2024). "We aimed to investigate the influence of body mass index (BMI) and serum albumin at ED presentation on the mortality risk of advanced cancer patients at the ED." (PMID 39414641, 2024).
cancer (continued). "Several biomarkers related to inflammation, such as the NLR, GPS, lymphocyte-CRP ratio, systemic inflammation response index, and CRP-albumin ratio, have been reported to be associated with prognosis in patients with a variety of cancers, including STS." (PMID 38473433, 2024). "Several basic science studies have elucidated why lower albumin levels can exacerbate the risk of cancer mortality." (PMID 38500655, 2024). "The Cox proportional hazards model was employed to evaluate the association between serum albumin levels and cancer mortality." (PMID 38500655, 2024). "Research into cause-specific mortality within the general community population has shown that low serum albumin levels are linked to increased cancer mortality." (PMID 38500655, 2024). "The aim of the study was to assess the role of albumin and prealbumin in assessing the nutritional status of cancer patients and in predicting an increased risk of infectious complications during treatment." (PMID 39619813, 2024). "The association of serum albumin with mortality was equally observed in men and women (P for difference = 0.071, P = 0.41, P = 0.015, and P = 0.44 for total, vascular, cancer, and other causes of mortality, respectively)." (PMID 39010980, 2024). "Subgroup analyses further validated the associations between albumin levels and cancer mortality, as observed in the current study, across a wide range of risk factors." (PMID 38500655, 2024). "Reduced serum albumin levels can be caused by infections, burns, liver illness, nephrotic syndrome, and cancers." (PMID 38384810, 2024). "Previous research has consistently identified an association between albumin levels and the risk of mortality across various cancer types." (PMID 38500655, 2024). "The same trend of a higher rate of deaths at lower serum albumin levels was observed for vascular, cancer, or other causes of mortality." (PMID 39010980, 2024). "The risk of cancer-related mortality increased as serum albumin, prealbumin and transferrin levels decreased." (PMID 38438901, 2024). "Abnormal blood test results associated with cancer included low albumin (positive likelihood ratio 3.24, 3.13 to 3.35) and raised platelets (3.48, 3.35 to 3.62), total white cell count (3.01, 2.89 to 3.14), and C reactive protein (3.13, 3.05 to 3.20)." (PMID 39414353, 2024). "Numerous investigations involving patients undergoing chemotherapy, surgery, targeted therapy, or radiotherapy have shown that lower albumin levels in cancer patients are associated with reduced overall survival (OS) and progression-free survival (PFS)." (PMID 39195131, 2024). "Serum albumin levels have reported associations with nutritional risk and systemic inflammatory responses and are prognostic factors in cancer." (PMID 39164514, 2024). "Currently, clinical studies on the association between ALB and ALP in patients with cancer are limited, and most studies have focused on the ALB/ALP ratio." (PMID 38552093, 2024). "Similar to previous studies, our study found a negative correlation between serum albumin concentration and T2D, as well as associations between serum albumin concentration and the prognosis of cardiovascular disease, cancer mortality, and all-cause mortality." (PMID 38282658, 2024). "We observed heterogeneity in the data reported for the other common risk factors as well, such as albumin, haemoglobin, late referral, cause of kidney disease and cancer." (PMID 39669010, 2024). "The present study reported that low albumin, prealbumin, and transferrin levels were associated with worse prognosis in patients with cancer cachexia." (PMID 38438901, 2024). "In terms of categorical analysis, multivariate Cox proportional hazards regression demonstrated that patients with albumin levels ≤ 4.2 g/dL carried a greater mortality risk than those with levels > 4.2 g/dL across all cancer groups." (PMID 38500655, 2024).
cancer (continued). "Individuals ≥65 years old with serum albumin levels ≤35 g/L are at higher risk of total, cancer, and vascular mortality." (PMID 39010980, 2024). "Lower levels of serum albumin, indicative of a malnourished state, have been associated with poorer survival outcomes in various types of cancers." (PMID 39553069, 2024). "The goal of this retrospective study was to identify patient-derived risk factors, especially focusing on serum albumin and body mass index (BMI) for 90-day mortality following unplanned ED visits by cancer patients." (PMID 39414641, 2024). "The present study, comprehensively assessed the association between albumin, prealbumin, and transferrin levels and prognosis in cancer cachexia patients for the first time." (PMID 38438901, 2024). "An association between serum albumin levels and PhA has been previously reported in hospitalized patients and patients with advanced cancer; however, an association between PhA and nutritional indices in healthy individuals is yet to be established." (PMID 37630789, 2023). "The Geriatric Nutrition Risk Index (GNRI) is an indicator mainly composed of serum albumin levels and body weight, which has the ability to predict the mortality risk of elderly patients with different cancers." (PMID 36815992, 2023). "The nutritional risk index (NRI), which is based on weight and albumin levels, is closely associated with prognosis in many cancers." (PMID 36441260, 2023). "The albumin concentration can reflect the nutritional status of the body and has been associated with the prognosis of several cancers." (PMID 36924334, 2023). "Another study analyzed the association between albumin, bilirubin, and uric acid levels and cancer risk in a prospective population-based study of 25,540 volunteers from Germany in the age range between 35 and 65 years." (PMID 37836494, 2023). "Several pre-operative factors were associated with FTR, including comorbidities, cancer diagnosis and pre-operative albumin levels." (PMID 37225931, 2023). "As early as 2010, a systematic review revealed that high albumin levels are associated with better outcomes in different types of cancer." (PMID 37128769, 2023). "The decrease in serum albumin level has been reported in some studies as a risk factor for cancer incidence." (PMID 37836494, 2023). "In the future, we would like to futher explore the underlying mechanism between preopetative albumin level and prognosis in GC cancer patients." (PMID 37007142, 2023). "Some studies also have found that there was an inverse association between albumin level and cancer incidence." (PMID 37908181, 2023). "In clinical practice, a change in albumin levels is often used for assessing prognosis in cancer care, and low levels are associated with a poorer prognosis." (PMID 37880704, 2023). "Because low levels of serum albumin are associated with poor outcomes in cancer patients, they can be used as an independent indicator when assessing the need for aggressive nutritional intervention." (PMID 37447236, 2023). "Evidence showed that in patients with cancer’ age, nutritional status, stage and type of cancer are factors associated with albumin, TP and Hgb level." (PMID 36869395, 2023). "Serum ALB levels can reflect systemic inflammatory response and nutritional status, and reduced ALB levels have been shown to be associated with poor prognosis in a variety of cancers." (PMID 37234992, 2023). "Low albumin levels favor the development of tumors and the inflammatory environment associated with cancer, leading to a poorer prognosis." (PMID 38112846, 2023). "As such, high serum albumin levels have been associated with improved 1-year mortality rates in cancer patients with cachexia." (PMID 36848404, 2023). "According to a study, low albumin levels are directly associated with poor prognosis and survival of breast patients with cancer." (PMID 36869395, 2023).